FOXP3 (forkhead box P3)
Diseases named in the same sentence as FOXP3 in open-access papers (continued):
Sharing a sentence is not in itself a finding about the gene and the disease.
tumor (continued). "Foxp3 with low expression (upper-right) and high expression (down-right) was seen in the nucleus of lymphocytes, most of which were located at the tumor margin." (PMID 23723999, 2013). "To analyze whether CD4, CD25, Foxp3, IL-10, and TGF-β expression in CRC may be associated with clinical tumor progression we investigated tumors of limited disease (UICC I/II) and advanced disease (UICC III/IV)." (PMID 23382847, 2013). "However, in other cancers, notably CRC, the presence and density of FOXP3+ Treg have been reported to predict favorable outcome and a better locoregional control of the tumor." (PMID 23730621, 2013). "A previous study showed that the local tumor immune microenvironment plays an important role in cancer suppression and promotion and that one of the main factors leading to tumor immune tolerance in the local tumor microenvironment is the influence of CD4+/CD25+/FOXP3+ regulatory T cells (Tregs)." (PMID 23759077, 2013). "Therefore, the purpose of this study was to evaluate Foxp3 expression between tumor infiltrating Treg and cancer cells in patients with CRC at different stages of the disease as well as to discriminate its prognostic significance over the long-term." (PMID 23382847, 2013). "Ambiguous data suggest that tumor infiltration by Foxp3+ Treg is not always associated with a poor prognosis, but, on the contrary, can be associated with an improved prognosis in some cancer types like in CRC." (PMID 23382847, 2013). "In addition, tumor-infiltrating Tim-3+Foxp3+ CD4 T cells expressed higher levels of CTLA-4, GITR and PD-1 compared with Tim-3−Foxp3+ CD4 T cells." (PMID 23526963, 2013). "CD4+CD25+FOXP3+ T regulatory (Treg) cells play an important role in the maintenance of self-tolerance and the modulation of overall immune responses against infections and tumor cells." (PMID 22489248, 2012). "We found that the majority of tumor-infiltrating FoxP3+ T cells were GFP+ tdTomato+ cells." (PMID 22292042, 2012). "Indeed, the frequency of CD4+CD25+FoxP3+ regulatory T cells was increased in lymph nodes of tumor-bearing LLA-TG-3 mice compared to tumor-free LLA-TG-3 mice." (PMID 22674057, 2012). "Alternatively, naïve T cells might be converted into Foxp3+ Treg cells in the tumor microenvironment." (PMID 23028615, 2012). "Thus, we demonstrate a complete demethylation of the FOXP3 promoter in colon Treg from tumor tissue, suggesting that the FOXP3+ cells stably express FOXP3 as part of an established Treg phenotype, and not due to recent activation of conventional T cells." (PMID 22319577, 2012). "However, Foxp3 levels in the splenocytes of the same tumor-bearing FTS-treated mice were significantly increased (by 69.3%±8.63%)." (PMID 22323550, 2012). "We showed blockage of TGF-β led to the inhibition of Foxp3 (+) T cells inside the tumor tissues." (PMID 22415727, 2012). "Interestingly, CD4+ FoxP3+ Helios+ Treg appeared to be relatively enriched in the tumor parenchyma as compared to corresponding spleens." (PMID 22479644, 2012). "Although studies have shown that PGE2 alone can directly induce FoxP3 expression, we believe there are many mechanisms, including directly recruiting Tregs to the tumor, which can ultimately manipulate the immune system to promote an immune-suppressive environment." (PMID 23029485, 2012). "To determine the role of CCR7 in population of lymphoid tissues and then eventually into tumors, we compared the abilities of CCR7 (+/+) and CCR7 (−/−) FoxP3+ T cells separately transferred into tumor-bearing scurfy mice, which lack FoxP3+ T cells and develop systemic inflammation." (PMID 22292042, 2012). "Interestingly, pMMR cases with FoxP3+high or CD8+high showed differences in tumor site and histologic grade compared to phenotypic characteristics of dMMR cases." (PMID 22879926, 2012).
tumor (continued). "Third, a Cy-sensitive Foxp3+CD25low effector/memory Treg sub-population present in tolerant mice is the primary mediator of antigen-targeted high avidity T cell suppression within the tumor microenvironment." (PMID 22359647, 2012). "The vaccine therapeutic efficacy was associated with tumor-specific killing activity, high frequency of IFN-γ secreting CD4+ T and CD8+ T cells, increased intratumoral number of CD4+ T and CD8+ T cells, and a decrease in the number of CD4+FoxP3+ Treg cells." (PMID 22870329, 2012). "Furthermore, they indicate that tumor infiltration by CD4+ or FOXP3+ cells is devoid of prognostic relevance." (PMID 22471961, 2012). "Furthermore, there are CD8+CD25+FoxP3+ T cells that appear uncommon in CRCs, and can suppress the anti-tumor immune response." (PMID 22879926, 2012). "Additionally, we show that COX2 over-expression in TM40D tumors alters their immune profile from a high infiltration of antitumor CD4+ T helper cells, to a high tumor frequency of suppressive CD4+ FoxP3+ Tregs." (PMID 23029485, 2012). "Contrasting data have been reported regarding FOXP3 expression in tumor cells." (PMID 22471961, 2012). "Our data indicate that CCR8 and CXCR4 are up-regulated on tumor-infiltrating FoxP3+ T cells." (PMID 22292042, 2012). "Within the B16 tumor, we found about 50% of the Foxp3+CD4+ TILs expressed Tim-3." (PMID 22363469, 2012). "Therefore, high expression of Helios by tumor FoxP3+ T cells most likely indicates the activation state of the T cells in tumors." (PMID 22292042, 2012). "In addition, following treatment with rhIL-2, a dramatic increase in CD8+ Foxp3+ T cell prevalence was observed in the circulation and tumor-draining lymph nodes of subcutaneous tumor-bearing mouse models." (PMID 23021024, 2012). "Vaccine efficacy was associated with robust tumor-reactive primary and memory CD8+ T effector responses, Th1 cytokine response, higher intratumoral CD8+ T effector/CD4+CD25+Foxp3+ T regulatory cell ratio, and reduced myeloid derived suppressor cells in the spleen." (PMID 22860107, 2012). "In contrast to the general increase of CD4+ T cells, the frequency of Foxp3 expressing cells within the CD4+ population was 4-fold lower in the vaccine-treated tumor than in the untreated tumor, while it was comparable in peripheral blood and spleen between the two groups." (PMID 23071764, 2012). "FoxP3+ T cells populate tumors and regulate anti-tumor immunity." (PMID 22292042, 2012). "When prior available MAL and bcl-2 expression data are included in a multivariate analysis of all clinical and biologic factors, a FOXP3/GrB ratio of 1 or less and tumor cell expression of MAL and bcl-2 all independently predicted poor failure-free survival (FFS)." (PMID 22151904, 2011). "A very low percentage (<1%) of CD8 T cells express Foxp3; this was unchanged in tumor-bearing mice." (PMID 22112546, 2011). "Alternatively, naïve Foxp3 T cells could be induced to express this regulatory transcription factor through tumor-derived signals yielding induced (i)Treg." (PMID 22112546, 2011). "It is, therefore, necessary to determine whether CD127 is also a better marker for enumerating FOXP3+ Treg cells in cancer patients in general by comparing Treg cells numbers in a larger number of different tumor subtypes." (PMID 21904560, 2011). "Here, we found that the level of FoxP3 was higher in tumor-derived Tregs." (PMID 21935436, 2011). "We hypothesized that naïve T cells entering the tumor microenvironment would be exposed to the signals and factors needed for induction of Foxp3 and the acquisition of a regulatory phenotype." (PMID 22112546, 2011). "Moreover, the CCL20 expression was strong correlated with the number of FoxP3+ Tregs in tumor environment." (PMID 21935436, 2011). "Correlation between tumor FoxP3+ cell and clinicopathologic characteristics." (PMID 21935436, 2011).
tumor (continued). "We used TCR transgenic mice - one devoid of CD4 nTreg and the other with < 1% Foxp3 CD8s - whose tumor-infiltrating T cells and perhaps those in lymphoid organs of tumor-bearing mice would be engaged by cognate antigen, as well as being exposed to tumor-produced TGFβ." (PMID 22112546, 2011). "The associations of clinical activity with increased TILs during treatment and with baseline expression of IDO and FoxP3 suggest that an immune-active tumor microenvironment might be necessary for a favorable response to ipilimumab." (PMID 22123319, 2011). "FOXP3+ T-cell density of the SLN tended to increase along with enlargement of tumour metastasis in SLNs; the difference in density within SLNs was statistically significant when comparing the cases having micrometastases or macrometastases in SLNs with those showing ITCs or negativity (P=0.001)." (PMID 21730981, 2011). "Importantly, the distribution of FoxP3+ cells in tumor region differed from that in non-tumor region." (PMID 21935436, 2011). "Moreover, antibody-mediated FoxP3 protein therapy resulted in a clinically significant reduction in tumor burden in a syngeneic model of colon cancer metastasis to liver in Balb/c mice." (PMID 21559338, 2011). "In summary, we generated two TCR transgenic mouse strains in which the de novo generation of iTreg could be unequivocally demonstrated in vitro, and in which putative signals for Foxp3 induction were present in the tumor microenvironment." (PMID 22112546, 2011). "Given the central contribution of FOXP3 to Treg function, the expression of FOXP3 by tumour cells may represent a novel mechanism by which cancers suppress the immune system to escape destruction." (PMID 21818290, 2011). "Thus, in patients of different types of NHL, the percentage and the function of tumor-infiltrating FOXP3+ T cells predicts different survival." (PMID 22151904, 2011). "Moreover, in humans, tumor antigen specific FoxP3+ Treg-cells have been successfully isolated from tumor tissues as well as peripheral blood of patients with melanoma and cervical cancer." (PMID 21559338, 2011). "The ontogeny of these enriched Foxp3-positive cells in tumor-bearing hosts is still a matter of controversy: do they represent thymus-derived natural Treg (nTreg) or induced Treg (iTreg) derived from naïve T cells in which Foxp3 expression is induced through some tumor-dependent mechanism?" (PMID 22112546, 2011). "The expression of Foxp3 and IL-10 mRNA increased significantly in tumor-bearing mice (P < 0.01)." (PMID 21963624, 2011). "Histological evidence indicates that anti-CTLA-4 activates the tumor vasculature and increases proliferation and infiltration of tumors by CD4+ and CD8+ (FoxP3-) effector cells, thereby increasing the ratio of effector T cells to Tregs in the tumor microenvironment." (PMID 21281484, 2011). "In addition, analysis of the clonal abundance accounts for over 70% of all Foxp3+ T cells in tumor tissues so it is unlikely that we missed some Treg clones that account for a large fraction of Foxp3+ cells in tumors." (PMID 21049016, 2010). "Foxp3 immunostaining demonstrated nuclear staining in a subset of lymphocytes around tumor tissues." (PMID 20064222, 2010). "Furthermore, we evaluated the ratio of tumor infiltrating CD8+ cells to Foxp3+ cells (the ratio of CD8/Foxp3) and Foxp3+ cells together with GrB + cells in predicting survival in all patients as well as in the patients with different disease stage." (PMID 20064222, 2010). "These opposing roles of IL-23R signaling on Foxp3 expression in the tumor and gut may reflect differences in the tissue microenvironments or the differentiation state of responding T cells." (PMID 20732640, 2010). "Interestingly, tumor samples from ECDα2 boosted mice shown smaller number of the ratio of Foxp3+/CD4+ (12%) compared with that of control mice (30%, P < 0.001)." (PMID 21067607, 2010).
tumor (continued). "Finally, the prime boost strategy was able to reduce immunosuppressive CD4+CD25+Foxp3+ regulatory T cells (Tregs) in the spleen and tumor of vaccinated mice." (PMID 21067607, 2010). "Moreover, it has recently been reported that DCs are capable of inducing conversion of naive CD4+ T cells to adaptive CD4+ CD25+ Foxp3+ Treg in the presence of TGF-β or IL-10 derived from tumor cells." (PMID 20182533, 2009). "Also, the number of cells staining positive for FoxP3 by immunohistochemistry increases in tumor biopsies of regressing lesions after CTLA4 blockade." (PMID 19457253, 2009). "Specifically, there were more Foxp3+ cells in SLN with metastasis than tumor-free SLN (20% v." (PMID 19604349, 2009). "There is accumulating evidence indicating that CD4+CD25+FoxP3+ regulatory T-cells (Treg) are able to induce tolerance to self-antigens and may also inhibit anti-tumour immune response." (PMID 19732435, 2009). "In survival analysis, patients with a high stromal CD68+/FoxP3+ cell ratio (> 2.9) at the primary tumour site had a median survival of 32 months while those with a lower CD68+/FoxP3+ cell ratio (< 2.9) had a median survival of 55 months (p = 0.008) (graph not shown)." (PMID 19732435, 2009). "Recent evidence suggests that CD4+CD25+FoxP3+ regulatory T-cells (Treg) may be responsible for the failure of host anti-tumour immunity by suppressing cytotoxic T- cells." (PMID 19732435, 2009). "Tumor-associated Tregs express the IL-23 receptor, which activates STAT-3 in this cell type, leading to upregulation of the Treg-specific transcription factor FoxP3 and the immunosuppressive cytokine IL-10." (PMID 19900287, 2009). "Furthermore, in murine models, FoxP3+ cells can play a positive role in anti-tumor and anti-viral immunity." (PMID 19641607, 2009). "Thus, by multiple analyses, tumor-infiltrating FoxP3+ cells showed a trend or statistically significant association with increased DSS." (PMID 19641607, 2009). "Because expression of Foxp3 has been reported in lung epithelial cells and some tumor cell lines, we co-stained lung tissues or lymph nodes for Foxp3 and CD3 expression, and confirmed that expression of Foxp3 was observed in CD3+ cells but not epithelial cells." (PMID 19330036, 2009). "In addition to the staining for FOXP3, all tumours were stained with antibodies against CD3 and CD8 to assess the overall infiltration with CD3-positive T cells and with CD8-positive T cells." (PMID 18985040, 2008). "For example, the cancer–stromal reaction including the migration factors for Foxp3+ T regs may differ within tumours, leading to the difference in the localisation pattern of Foxp3+ T regs." (PMID 18087278, 2008). "Furthermore, in terms of the localisation pattern of accumulating Foxp3+ cells in tumours, we classified all cases into three groups: a peri-tumour group (n=30), a diffuse group (n=40), and a follicular group (n=10)." (PMID 18087278, 2008). "The expression of FOXP3 in T cells corresponds with immune regulatory function, indicating that the number of FOXP3-positive tumour-infiltrating lymphocytes is representative of the number of potential immune suppressor T cells in the tumour microenvironment." (PMID 18985040, 2008). "In addition, the distribution pattern of B7-H1+ TIL was different from that of FOXP3+ Tregs; Tregs were single cells distributed over the section of the tumor tissues while B7-H1+ TIL aggregated in clumps." (PMID 18294387, 2008). "We offer evidence that Foxp3 expression, characterizes tumor cells of various tissue origins." (PMID 18430198, 2008). "A dense infiltration of MSI-H CRCs with FOXP3-positive cells may play a role in local MSI-H tumour growth in the presence of potentially cytotoxic T cells in the local tumour environment." (PMID 18985040, 2008). "This study was scheduled to investigate whether expression of Foxp3 transcripts and mature protein occurs constitutively in various tumor types." (PMID 18430198, 2008).
tumor (continued). "Then, localisation patterns of infiltrating Foxp3+ cells were divided into three groups: a peri-tumour group (n=30), diffuse group (n=40), and follicular group (n=10), in terms of where Foxp3+ cells dominantly occupied the lesion by immunohistochemistry as described in Materials and Methods." (PMID 18087278, 2008). "Also in MSI-H CRCs, a higher proportion of the tumour-infiltrating FOXP3-positive cells were located in the epithelium, as indicated by a higher ratio of epithelial-to-stromal infiltration in the MSI-H group." (PMID 18985040, 2008). "Interestingly, tumours with a diffuse distribution pattern of Foxp3+ cells were more frequent in stages II+III+IV, while tumours with a peri-tumoral distribution pattern of Foxp3+ cells were more frequent in stage I (P<0.05 by the χ2 test)." (PMID 18087278, 2008). "There was a correlation between B7-H1 in tumor cells and FOXP3+ Tregs (P < .019)." (PMID 18294387, 2008). "The correlation of the expression B7-H1 in tumor cells and FOXP3+ Tregs was also studied." (PMID 18294387, 2008). "Infiltration of the tumour with FOXP3-positive cells was observed in all CRC specimens." (PMID 18985040, 2008). "However, the abundance of T-regulatory cells (Tregs) depends on the presence of lymphoid tissue around the tumor, and the role of FoxP3 Tregs in immune suppression may depend on the secretion of IL-12 and TGF-β in the tissues." (PMID 41511327, 2025). "Notably, high B7-H3 expression—both in tumor cells and vasculature—was associated with poor prognosis in FOXP3+ high groups, contrarily showing no significant prognostic impact in FOXP3-low samples." (PMID 40801642, 2025). "Thus, short-term systemic depletion of Foxp3 protein induces a localized anti-tumor immune response without causing significant T cell expansion or loss of GFP+ TREG cells elsewhere in the body." (PMID 40478934, 2025). "In this regard, the transgenic C57Bl/6-FoxP3-eGFP mouse line, in which FoxP3 expression is accompanied by eGFP fluorescence, appears to be an ideal platform for the intravital study of Treg activation and inactivation mechanisms during tumor development, including the intravital microscopy method." (PMID 40071070, 2025). "In addition, the upcoming possibilities to modify compounds with other small molecules, such as PROTACs, to specifically target FoxP3 degradation in tumor-infiltrating Tregs24,36 could be an alternative strategy to achieve higher selectivity and less toxicity." (PMID 40034859, 2025). "Preclinical models demonstrated complete tumor regression and sustained immunological memory in 40–60 % of anti-CTLA-4-treated mice, effects mechanistically linked to enhanced CD8+ effector T cell/Treg ratios (4.8 vs. 1.6 in controls) through FoxP3+ cell depletion." (PMID 41209702, 2025). "Moreover, the proportion of Tregs (CD3+CD4+FoxP3+) in the combined treatment group significantly decreased compared to that in the model (p < 0.001) and PDT (p < 0.05) groups, confirming a reduction in tumor-associated immunosuppression." (PMID 40746718, 2025). "Interestingly, we observed lower Foxp3 gene expression by RNA-seq in AMPK-deficient Treg cells isolated from the TME at day 12 but not at day 15, suggesting important regulatory events occurring over the course of tumor growth." (PMID 40100289, 2025). "Consequently, CD8+FoxP3+ cells might have a specialized role and occupy a unique niche in the context of T-cell exhaustion and tumor immune modulation." (PMID 40422521, 2025). "Moreover, HA@CD36i‐TR@siSCD1 had a potent immune‐enhancing effect, increasing the proportion of CD8+ T cells, decreasing the number of CD4+FoxP3+ Treg cells, promoting the release of the tumor killer factors TNF‐α and IFN‐γ, and transforming refractory PCa from “cold” tumors to “hot” tumors." (PMID 39736148, 2025).